ARG1 (arginase 1)
Diseases named in the same sentence as ARG1 in open-access papers (continued):
Sharing a sentence is not in itself a finding about the gene and the disease.
tumor (continued). "M2 macrophages express high levels of IL-10, TGF-β, ARG1, and other related factors that promote tumor growth, which can not only induce immune escape, angiogenesis, tumor growth, and metastasis but also lead to resistance to checkpoint inhibitors or adoptive T cell immunotherapy." (PMID 39596288, 2024). "In addition, overexpression of YAP1 induces the polarization of macrophages into the M2 phenotypes (tumor-associated macrophages) by regulating different genes such as iNOS, MerTK, IL-10, STAT3, CD163, CD206, Arg-1, CD86, and TNF-α in the naive macrophages." (PMID 39630608, 2024). "Additionally, patients with high TBC1D1 expression exhibited increased infiltration of M2 tumor-associated macrophages (TAMs), showing significant elevation in markers including CD68 and ARG1." (PMID 38529286, 2024). "Moreover, pro-tumour Arg1+ microglia reduced, and rAAV2-IL-15 microglia became more branchy and far-reaching." (PMID 38212785, 2024). "However, with LNP-CTNNB1 treatment, tumor cells begin to express zone 1 markers, including Cyp2f2, Arg1, and Ass1, while decreasing expression of zone 3 genes (e.g., Cyp2e1, Cyp1a2, and Oat)." (PMID 39711542, 2024). "Finally, murine G-MDSCs have been found to release ARG1 in small extracellular vesicles, which is a phenomenon currently only observed for ARG1-expressing tumor cells in the human setting." (PMID 39211039, 2024). "Also, the Arg1 and NO levels were notably reduced, which was in line with the significant reduction in tumor growth." (PMID 39329901, 2024). "Conversely, IMs undergo a shift in their gene expression from an initial pro-inflammatory state, characterized by upregulation of genes such as SOCS1 and downregulation of CD38, IGF1, andCD206, to a later tumor-promoting profile, with substantial induction of Arginase-1." (PMID 38229178, 2024). "Arginase 1(Arg-1) is another molecule produced by M2 macrophages, which creates an immunosuppressive environment by metabolizing L-arginine, thereby impairing T cell function and promoting tumor growth." (PMID 38713256, 2024). "Rich granules in neutrophils, such as MMP‐9 and ARG‐1, have been shown to promote tumor growth." (PMID 38553949, 2024). "Moreover, stimulation with mouse-derived recombinant SPP1 protein induced the expression of pro-tumor genes (such as Arg1, Slc2a1, and Nos2) in MDSCs while repressing the expression of anti-tumor genes (such as Il1b, Tnfa, and Il12b)." (PMID 39066845, 2024). "MDSCs suppress anti-tumour immunity through a plethora of mechanisms including the well-characterised arginase 1 (Arg1), inducible nitric oxide synthase (iNOS) and reactive oxygen species (ROS)-mediated pathways, along with several other more recently discovered." (PMID 38464388, 2024). "The coexpression of ARG1 and inducible nitric oxide synthase (iNOS) enhances the production of ROS and reactive nitrogen species, which further inhibits the function of T cells within tumor cells." (PMID 39192979, 2024). "Cancer cell-derived lactate can induce the expression of vascular endothelial growth factor (VEGF) and arginase 1 (Arg1) through HIF-1α signaling pathway, which promotes the polarization of tumor-associated macrophages (TAMs) toward the M2 phenotype, enabling TAMs to promote tumor growth." (PMID 38287402, 2024). "M2-type macrophages then secrete epidermal growth factor receptor (EGFR), transforming growth factor-β (TGF-β), vascular endothelial growth factor (VEGF), platelet-derived growth factor (PDGF), IL-10, IL-6 and arginase-1, promoting tumor angiogenesis and tumor progression." (PMID 38792234, 2024). "On the other hand, CD206-expressing monocytic cells are classically associated with an anti-inflammatory phenotype, as described for in vitro differentiated regulatory macrophages or infiltrating CD14+ CD206+ tumor monocytes, which specifically express Arginase-1, IL-10, and TGFβ." (PMID 39845960, 2024).
tumor (continued). "Additionally, we isolated macrophages from untreated 2153L and 2151R tumors and found that zotatifin treatment suppressed the expression of Arg1 and CD206 in these tumor-associated macrophages (TAMs)." (PMID 37874652, 2023). "Furthermore, TAM polarization was examined by gating the tumor cell suspensions with M1 (CD11b + F4/80 + iNos+) and M2 (CD11b + F4/80 + Arg1+) macrophage markers." (PMID 37264310, 2023). "In addition, we have observed both decreased ARG1 expression and reduced suppressive function of tumor-educated myeloid cells after vaccination." (PMID 36175673, 2023). "Furthermore, we confirmed that arginase-1 gene expression levels of GFP+CD45− tumor cells from Arg1 OE CT26 cell-inoculated mice were higher compared to the mock control from mice." (PMID 36639644, 2023). "Importantly, we would need to extend this study's results to a bigger cohort of cancer patients to validate ARG1-positive cells as a marker of an immunosuppressive tumour microenvironment." (PMID 37980483, 2023). "However, in those studies, high level of ARG1 was attributed to the whole tumours, requiring further investigations to determine ARG1-positive cell type and prognostic value of infiltrating ARG1-positive cells." (PMID 37980483, 2023). "In addition to its direct effect on tumor growth, Arg-1 further fosters tumorigenesis by inducing immune suppression; it depletes arginine, which is essential for T-cell proliferation, in the TME." (PMID 38001706, 2023). "We discovered that deletion of Arg1 in myeloid cells reduced progression to invasive disease, conversely resulting in accumulation of early lesions with prominent Tuft cells, a cell type that is protective toward tumor progression." (PMID 36727849, 2023). "Indeed, we observed that the expression of arginase-1 (Arg-1) was significantly up-regulated in tumor compared to blood and bone marrow neutrophils." (PMID 36614196, 2023). "BMDM or the macrophage cell line Raw264.7 was co-cultured with PY8119 cells to mimic the TNBC microenvironment in vitro, and macrophages were polarized toward pro-tumor M2 phenotype and M2 markers Arg-1, CD206, Fizz-1, Ym1 and IL-10 were upregulated significantly." (PMID 37925462, 2023). "Consistently, ARG1 protein-positive cells were more abundant in 66cl4 tumours." (PMID 37980483, 2023). "Immunoregulatory Arginase-1 (Arg-1) is present in the tumor microenvironment of solid tumors." (PMID 38001706, 2023). "Therefore, HDAC inhibitors have been reported to increase the efficacy of immune checkpoint inhibition by downregulation of Arg1 in pro-tumor neutrophils." (PMID 37496019, 2023). "PMN-MDSCs which were originated from immature myeloid cells of the bone marrow could migrate to TME to promote resistance to CD8 + cells and enhance the immune escape of the tumor via production of immunosuppressive enzymes such as Arg-1 and iNOS." (PMID 37880708, 2023). "Arg1 has been described as a marker of M2 macrophages, present in both healthy and tumor tissue." (PMID 37048119, 2023). "Tumours in ARG1 KO mice were 50% smaller than those in wild-type mice." (PMID 37723490, 2023). "The low arginine:ornithine ratio suggests elevated ARG1 enzymatic activity in 66cl4 tumours." (PMID 37980483, 2023). "Thus, high Arg-1 levels in the tumor are expected to reflect highly active metabolism, rapid arginine utilization and rapid tumor growth." (PMID 38001706, 2023). "We examined how tumor cells utilize Arg-1 for the catalysis of exogenous arginine." (PMID 38001706, 2023). "To test our hypothesis, we quantified the ARG1 protein levels in plasma from healthy and tumour-bearing mice using ELISA." (PMID 37980483, 2023). "Furthermore, the expression or activity of MDSCs-associated molecules (ARG1, CYBB, iNOS, IL-10, NCF4, and TGF-β2) were significantly decreased from GPR84−/− mice in both LLC and B16F0 tumor models." (PMID 37105980, 2023). "Arg-1 is recognized as both a promoter of tumor growth and inhibitor of anti-tumor immunity." (PMID 38001706, 2023).
tumor (continued). "The mRNA expression levels of genes characteristics of a tumor-supportive macrophage phenotype, including Arg-1, were also downregulated by shMYBL2-CM, while those of the cytotoxic response-related genes IL-1β, IL-12 A, and CD86 were increased by supernatants of shMYBL2 cells." (PMID 37865750, 2023). "Combination therapy elicited dramatic changes in both the myeloid and lymphoid compartments of the tumor microenvironment, including decreased infiltration of neutrophils and Arg1+ macrophages and increased infiltration of eosinophils, NK cells, CD8+ T cells, and CD4+ T cells." (PMID 37874652, 2023). "ARG1 could inhibit T cell activation and proliferation, leading to T cells dysfunction and allowing tumor cells to escape." (PMID 38012650, 2023). "ARG1-positive tumours were also found primarily in the upper quartiles of mitotic counts per high-power field, with 10/33 (30%) of the tumours having mitotic counts per HPF in the 3rd quartile and 13/33 (39%) with mitotic counts per HPF in the 4th quartile (p < 0.001)." (PMID 37980483, 2023). "In contrast, ARG1 is highly expressed in M2 macrophages and metabolizes arginine into urea, polyamine, and ornithine, which are involved in macrophage repair and play immunosuppressive roles in assisting tumor invasion." (PMID 37366304, 2023). "On the basis of these findings, we speculate that inhibition of ARG1 will show effective antitumor effects from two directions in a tumor-bearing host." (PMID 36639644, 2023). "The few Arg1 mRNA-positive cells we observed in 67NR tumours, were also localised in the periphery." (PMID 37980483, 2023). "Although cells positive for Arg1 mRNA and ARG1 protein predominantly localised in the tumour periphery, the deeper infiltration of ARG1 protein containing cells may suggest involvement of various cell types or cells of different maturation/activation stage." (PMID 37980483, 2023). "All patients with low tumor and high plasma Arg-1 had nodal metastases and developed recurrence." (PMID 38001706, 2023). "A total of 20/33 (61%) ARG1-positive tumours were found among the Ki67 high tumours (p = 0.04)." (PMID 37980483, 2023). "So, ARG1-positive cells observed in the lungs may be myeloid cells that migrate from the tumour, and they are presumably indicative for early steps in the metastatic process." (PMID 37980483, 2023). "In contrast, the pro-tumor TANs have higher levels of Arginase 1 (Arg1), CD206, Ym1, IL-6, CCL17, CXCR4, neutrophil elastase (NE), matrix metalloproteinase 9 (MMP9), vascular endothelial growth factor (VEGF), and the neuropeptide prokineticin 2 (PROK2, also known as Bv8)." (PMID 37496019, 2023). "While U0126 treatment alone did not appear to inhibit ARG1 levels in the tumor lysates, its combination with poly(I:C) markedly reduced the treatment-associated ARG1 induction." (PMID 36726024, 2023). "Whether this subset of Arg1-expressing macrophages plays an important role in the tumor microenvironment warrants further study in the future." (PMID 36639681, 2023). "In addition, the ARG1 blockade in tumor mouse models favoured tumor rejection following adoptive cell therapy (ACT)." (PMID 37872395, 2023). "To the best of our knowledge, we are the first to report that plasma-derived exosomes from HNSCC patients carry Arg-1, thereby supporting our hypothesis of Arg-1 export from the tumor to plasma via exosomes." (PMID 38001706, 2023). "The production of iNOS and Arg-1 by MDSCs has been reported to be a major inhibitory mechanism, which mediates the formation of immunosuppressive microenvironment, we also found that JPYZXZ could decrease the expression of iNOS and Arg-1 in tumor tissues." (PMID 37601051, 2023). "We found a small number of ARG1 protein positive cells in the lungs of metastatic tumour-bearing mice, which could indicate early migration of these cells from the tumour to establish the pre-metastatic niche." (PMID 37980483, 2023).
tumor (continued). "MDSCs expressing ARG1 can alter T-cell activation and enhance tumor invasion." (PMID 37598273, 2023). "ARG1-positive tumours (≥ 10 cells) were observed among all molecular subtypes." (PMID 37980483, 2023). "In metastatic 66cl4 tumours, ARG1 is predominantly expressed by infiltrating immune cells." (PMID 37980483, 2023). "In addition, myeloid inhibitory cells (MDSCs) are diverse bone marrow progenitor cells that produce arginase 1 (ARG1) to promote tumor cell growth and suppress immune cell function." (PMID 37359529, 2023). "Mechanistic studies reveal that Fe-CDs can selectively promote tumor cell apoptosis through regulating PARP/Caspase 3/Caspase 9/BAX proteins, and activate antitumoral macrophages by inhibiting the IL-10/Arg-1 axis, which contributed to the superior anti-tumor performance of Fe-CDs." (PMID 37978538, 2023). "Previous findings in tumor patients and murine tumor models suggested that Arg1-mediated suppressor activity may be largely exerted by G-MDSC, while iNOS-mediated suppression is a major feature of M-MDSC." (PMID 37275910, 2023). "When ARG1 activity is enhanced in tumour cells and leads to low L-arginine concentrations, the NOS reductase domain may generate superoxide." (PMID 37723490, 2023). "Arg1 is another key factor of immunosuppressive myeloid cells and tumor cells." (PMID 37277776, 2023). "In TME, high levels of ARG1 expression promoted tumor growth and metastasis." (PMID 38012650, 2023). "Following intratumoral injection into B16F10-bearing mice, the DOX-loaded mPEG-b-PLNVal hydrogel showed inhibition effect on the arginase 1 in tumor and strengthened the antitumor immune response, which was elicited by DOX-induced immunogenic cell death (ICD) of tumor cells." (PMID 37265604, 2023). "Furthermore, flow cytometric analysis showed that ARG1 was mainly expressed in CD45+ cells in MC38 tumor, suggesting that the majority of ARG1 was derived from CD45+ cells." (PMID 38012650, 2023). "Tumor-associated neutrophils are capable of suppressing innate and adaptive lymphoid cell function by producing ROS, reactive nitrogen intermediates (RNI), ARG1." (PMID 37252189, 2023). "We hypothesised that in our mouse model, ARG1 could also be released from tumour-infiltrating immune cells and leaked into the plasma, affecting arginine levels systemically." (PMID 37980483, 2023). "ARG1 promotes tumour cell proliferation by enhancing the production of L-ornithine and putrescine." (PMID 37462801, 2023). "Several oncogenic lncRNAs can promote tumor progression by affecting M2 polarization and Arg1 expression, such as lncRNA AK0363962, lncRNA CRNED, lncRNA X inactive specific transcript (XIST), lncRNA NEAT1, lncRNA runt-related transcription factor 1 overlapping RNA (RUNXOR)." (PMID 37127605, 2023). "Current research suggested that ARG1 was over-expressed in tumors at the stage of rapid tumor development, which strongly impeded the function of T cells and presents a state of exhaustion, but its relevance to immune checkpoint has not been thoroughly studied." (PMID 38012650, 2023). "Strategies involving the use of ARG1 inhibitors to reinvigorate M1 immunity may, in turn, reactivate tumor-specific Th1 immunity and restore cytotoxic activity." (PMID 38259478, 2023). "N1-type neutrophils kill tumor cells via antibody-dependent cell-mediated cytotoxicity after the initiation of an adaptive response, while N2-type cells have been reported to inhibit T cell activation by inducing arginase 1 (ARG1) and ROS." (PMID 37646231, 2023). "Finally, we confirmed that Arg1 gene expression was higher in tumor tissues of liver metastasis than in those of the primary tumor of CRC patients." (PMID 36639644, 2023). "Interestingly, ARG1 protein levels in the metastatic tumour also correlated with its levels and activity in plasma." (PMID 37980483, 2023).
tumor (continued). "However, in metastatic PDAC when the tumor is extensively evolved, MDSCs and Arg-1+ M2-like macrophages represent the main contributors of immunosuppression, which suggests impaired innate immunity at this stage." (PMID 35316682, 2022). "Additionally, the quantity of ROS and arginase-1 were more ascendant in tumor mice than the naïve controls, showing a strong suppressive capacity against CD8+ T cells." (PMID 35053426, 2022). "Furthermore, a 0.15 overall survival probability was identified for patients with high CD86 gene expression in tumor specimens vs. 0.3 for low expression, and 0.25 vs. 0.17 correspondingly in patients with high and low Arg1 gene expression in tumors." (PMID 35884700, 2022). "We also conducted the Western blot to examine the level of Arg-1 in the mice tumor tissues." (PMID 35154567, 2022). "Tumor-derived ANXA2 drives Arg1 gene expression in neutrophils." (PMID 36377658, 2022). "Conversely, M2 macrophages are identified by their ability to suppress anti-tumor responses by producing IL-10 and TGFβ, recruiting Tregs and Th2 cells, supporting fibrosis to exclude CTLs, sequestering L-arginine through Arginase-1 (Arg-1), and expressing immune checkpoint molecules." (PMID 36248881, 2022). "Phosphodiesterase-5 (PDE-5) inhibitors, such as sildenafil or tadalafil, have been reported to reduce the expression of arginase-1 and iNOS and thus inhibit the immune escape mechanism mediated by MDSCs while restoring T cell proliferation and inducing tumor cell apoptosis." (PMID 35053426, 2022). "Our data demonstrated that GPX8 was correlated with mRNA expression of immune markers of CD8+ T cells (CD8B), CD4+ T cells (CD4), T cells (CD3D), macrophages (CD68 and ARG1), neutrophils (ITGAM and CCR7), dendritic cells (NRP1), NK cells (B3GAT1), and tumor-associated fibroblasts (FAP)." (PMID 36061208, 2022). "Furthermore, CD163+ functional TAMs can be developed in tumor-bearing IL-6 transgenic mice and have produced high levels of immunosuppressive molecules, such as arginase-1 (Arg-1), IL-10, and VEGF." (PMID 35740551, 2022). "In addition to tumor cells, immunosuppressive cells expressing arginase 1 form an inhibitory immune barrier." (PMID 35898872, 2022). "In a mouse lung tumor model, inhibition of Arg-1 in myeloid cells diminished growth of established tumors by increasing T-cell infiltration into the tumor tissue, which was accompanied by a significant increase in the CD8/Foxp3 ratio and IFN-γ production in T cells isolated from the tumors." (PMID 35092727, 2022). "However, doxorubicin treatment upregulated M1 marker MHC-II, inducible nitric oxide synthase (iNOS) and CD86, and downregulated M2 marker Arginase 1 and CD206 on tumor-associated macrophages." (PMID 36274066, 2022). "To explore whether gene expression changes were specifically attributed to the GAMM population, we costained free-floating tumor sections for Arg1/Iba-1 or iNOS/Iba-1." (PMID 35113813, 2022). "Mechanistically, the IL-9/macrophage axis requires arginase 1 (Arg1) to mediate tumor growth." (PMID 35778404, 2022). "Also, MDSC can inhibit T cell-mediated adaptive anti-tumor immunity through the high expression of ARG1, iNOS, and ROS." (PMID 35222443, 2022). "The results of our study showed that BCLC stage, tumor size, the presence of multiple tumors, platelet count, and plasma ARG1 level as shown by our univariate analyses may be predictive factors for early TACE refractoriness." (PMID 36212404, 2022). "Tumor-derived COX-2 conduces arginase-1 induction of MDSCs, resulting in tumor immune tolerance." (PMID 35053426, 2022). "The activation of arginase-1-specific T cells may convert the immunosuppressive tumor microenvironment and induce or strengthen local Th1 inflammation." (PMID 36330525, 2022). "One interesting strategy could be to increase T cell immunity against ARG1-expressing cells, such as tumor and myeloid cells." (PMID 35159363, 2022).